POSTN (periostin)
Diseases named in the same sentence as POSTN in open-access papers (continued):
Sharing a sentence is not in itself a finding about the gene and the disease.
cancer (continued). "Given that TW functions relevant to EMT are regulated through site-specific phosphorylation (such as S68) and TW dimer motifs in other cancers we sought to define their potential roles in regulating POSTN expression and invasive phenotypes in GBM." (PMID 31540485, 2019). "Non-structural ECM proteins known as matricellular proteins, such as tenascin C and periostin are also expressed by CAFs, and their effects on cancer development has widely been reported." (PMID 31137693, 2019). "It was reported MiR-1205 can be sponged by hsa_circ_0039411, hsa_circ_0034642, hsa_circ_0002052, has_circ-POSTN, and hsa_circMAN2B2 in various cancers to regulate tumorigenesis and progression." (PMID 31801947, 2019). "Since POSTN plays multiple roles in cancer progression, targeting POSTN can be an attractive therapeutic approach." (PMID 29946533, 2018). "Periostin is found in normal adult tissues such as aorta, stomach, breast, lung, thyroid, colon, ovary and prostate, whereas it is overexpressed in various cancer types including neuroblastoma, head and neck, colon, thyroid, ovarian and breast cancers." (PMID 29774119, 2018). "The levels of serum POSTN in patients with cancer were significantly elevated compared to healthy controls and patients with benign lung disease." (PMID 29946533, 2018). "In GBM and other cancers, POSTN signals through integrin receptors and in other cancers can activate AKT." (PMID 29754406, 2018). "Taken together, these studies suggest that POSTN can act as a chemoattractant for cancer cells and that it is a key factor in metastatic colonization by conditioning of the premetastatic niche." (PMID 29946533, 2018). "For example, cancer cells that overexpressed POSTN were resistant to deferoxamine treatment, which mimic hypoxia." (PMID 29946533, 2018). "For example, periostin (POSTN), which has previously been reported to promote cell motility in several cancer types, was 13‐fold higher expressed in the metastases compared to nondiseased tissue." (PMID 29901861, 2018). "The deregulation of POSTN expression in many cancers suggests that it plays an important role in cancer development and progression." (PMID 29946533, 2018). "In this article, we will review the role of the matricellular protein POSTN in cancer development and progression in light of the hallmarks of cancer." (PMID 29946533, 2018). "POSTN has been shown to bind integrins αvβ3 and αvβ5 in osteoblasts and several types of normal and cancer cells where it elicits activation of FAK, PI3-Kinase, and AKT signaling pathways." (PMID 29946533, 2018). "To understand how periostin confers chemoresistance in mesenchymal cancer cells, we analyzed tumors one or three days after one dose of PTX treatment." (PMID 29507310, 2018). "We also confirmed the secretion of periostin from fibroblasts We then investigated the effect of interactions between these lung fibroblasts and cancer cells in a co-culture assay." (PMID 30131847, 2018). "To confirm the effect of periostin on cancer-cell proliferation, we assayed Ex3LL-cell proliferation in vitro." (PMID 30131847, 2018). "To investigate the relationship between cancer cells and the secretion of periostin from adjacent fibroblasts, we measured the periostin expression from fibroblasts cultured in medium conditioned by cancer cells." (PMID 30131847, 2018). "Periostin was reported to have an important role in wound repair and the epithelial-mesenchymal transition of cancer cells." (PMID 28842563, 2017). "In cancer tissues, periostin mRNA and protein expression were increased compared with adjacent normal tissues." (PMID 29161296, 2017). "Metformin significantly inhibited in vivo progression of heat-exposed residual HCC via suppressing POSTN secretion and decreasing cancer stem cell marker expression." (PMID 28526827, 2017).
cancer (continued). "It has been reported that some specific organs such as bones or periodontal ligament, or some cancer cells, show different expression profiles of periostin compared to other tissues or to normal cells." (PMID 28355256, 2017). "Reports have indicated that periostin is involved in cancer cell survival, epithelial–mesenchymal transition (EMT), ECM degradation, invasion, and distant metastasis." (PMID 29161296, 2017). "We found that periostin levels in EVs of pT1 cancers are greater than controls and six-fold below those of EVs from the MIBC urine specimens (P < 0.033)." (PMID 26981774, 2016). "As such, during the interaction between fibroblasts and cancer cells, the increased stromal POSTN induced by TGF-β3 directly accelerated the growth, migration and invasion of cancer cells." (PMID 26857387, 2016). "Overall, the induced-expression of POSTN in the ECM allowed for foreign cancer cell maintenance and facilitated the growth, migration and invasion of HNC cells." (PMID 26857387, 2016). "POSTN expression in cancer cells (epithelial POSTN expression) can promote metastatic potential of CRC, via activating the PI3 kinase (PI3K)/protein kinase B (Akt) signaling pathway." (PMID 26556874, 2016). "In this study, POSTN protein immunoreactivity observed in cancer stromal cells was found to be a predictive marker for platinum response and survival prognosis." (PMID 26716408, 2016). "In the present study, POSTN can be stained either in stromal cell and cancer cells in vivo with positive correlation." (PMID 26716408, 2016). "Like other cancer biomarkers such as α-fetoprotein, POSTN is actively expressed in a specific temporal and spatial pattern during embryogenesis, silenced after birth, and re-expressed in response to mechanical stress or carcinogenesis." (PMID 26556874, 2016). "Periostin has previously been shown to stimulate cancer metastatic growth by inducing the integrin αvβ3-AKT/ERK-mediated signaling pathway." (PMID 26981774, 2016). "Here, we found high levels of POSTN expression in cancer stroma was correlated with advanced disease stage, which is often associated with peritoneal and distal metastasis." (PMID 26716408, 2016). "Migrating myofibroblasts in response to TGF-β express periostin that binds to stromal Wnt ligands and presents it to cancer cells." (PMID 27486983, 2016). "Neutralizing monoclonal antibody against POSTN was shown to inhibit anchorage-independent growth and survival of POSTN-expressing cells and its neutralizing effects also suppress cancer cell migration and invasion." (PMID 26716408, 2016). "Periostin is an ECM component that is commonly over-expressed in a variety of cancers and is believed to be involved in cancer growth and metastasis." (PMID 26863567, 2016). "More recent studies have indicated that the overexpression of POSTN is frequently observed in numerous cancers, including breast cancer, melanoma, colon cancer, gastric cancer etc." (PMID 26857387, 2016). "Tenascin C (TNC) a hexameric glycoprotein and periostin are ECM components that play crucial role in metastatic niche in mouse cancer models." (PMID 27486983, 2016). "Taken together, we found high POSTN expression in cancer microenvironment is correlated with poor prognosis in EOC patients and associated with platinum resistance." (PMID 26716408, 2016). "Simultaneously, rhPOSTN drastically facilitated the migration and invasion of HN13 and Rca-T cells, while POSTN antibody partly decreased the migration and invasion of cancer cells." (PMID 26857387, 2016). "More optimal surgery were achieved in patients with low POSTN expression in cancer stromal cells (p = 0.025)." (PMID 26716408, 2016). "As a ligand for integrins, periostin mainly promoted cancer cells invasion and metastasis via integrin pathways." (PMID 27034956, 2016).
cancer (continued). "Stromal POSTN was found to connect the metastatic niche and cancer stem cell to create a cancer stem cell (CSC) -supportive niche and promote metastatic colonization by augmenting the Wnt signaling pathway." (PMID 26716408, 2016). "The ECM protein periostin, which is abundantly expressed by a large number of different human cancers, binds and neutralizes DCN." (PMID 26697491, 2015). "It has been frequently reported lately that POSTN is overexpressed in various types of human malignant tumors." (PMID 26023718, 2015). "Recently, it has been revealed that POSTN is overexpressed in various human cancers, including neuroblastoma, as well as head and neck, nasopharyngeal, thyroid, oral, breast and ovarian cancers." (PMID 26023718, 2015). "That is, high expression of periostin by PSC will induce EMT, migration metastasis and stemness of the cancer cells; whereas, low doses of periostin will do the opposite." (PMID 26029109, 2015). "Applying WGCNA to publicly available EAC microarray datasets has identified periostin to have a 'nodal' position within ECM gene expression in EAC, with close associations with genes involved in cancer cell invasion, adhesion and locomotion." (PMID 25345775, 2015). "Periostin stimulated cancer cell growth and induced their chemoresistance as well as resistance to starvation and hypoxia." (PMID 26029109, 2015). "Other studies have suggested that periostin expression is correlated with cancer metastasis and the bleak prognosis." (PMID 25781169, 2015). "Periostin, a secreted extracellular matrix protein, is highly expressed in wound healing and in various types of human cancer and is involved in angiogenesis." (PMID 25369801, 2015). "Previous observations demonstrated a correlation between high expression of Periostin and poor cancer-patient prognosis." (PMID 26543579, 2015). "In particular, we found that knockdown of periostin results in translocation of decorin from the cytoplasm to the extracellular space, leading to the inhibition of cancer cell migration and invasion." (PMID 25400079, 2014). "Stromal periostin has also been indicated to play a critical role in metastatic colonization, by regulating the interactions between cancer stem cells and their metastatic niche." (PMID 24146092, 2014). "In this report, we describe a novel function of periostin: tethering of free decorin in the cytoplasm of cancer cells, thereby preventing release of decorin to the extracellular space." (PMID 25400079, 2014). "Because secreted decorin inhibits cell motility and invasion, the results of our study suggest the importance of periostin as a potential therapeutic target in cancer cells that express both decorin and periostin." (PMID 25400079, 2014). "Periostin expression dramatically enhances metastatic growth of colon cancer by both preventing stress-induced apoptosis in cancer cells and augmenting endothelial cell survival to promote angiogenesis." (PMID 24901008, 2014). "Our mechanistic studies demonstrated that siRNA knockdown of periostin abolishes the interaction with decorin, thereby increasing the level of decorin secreted from cancer cells." (PMID 25400079, 2014). "This corresponded to the location of periostin previously identified in other types of cancer cells." (PMID 24273600, 2013). "POSTN potently promotes the metastatic development of colon cancer by both preventing stress-induced apoptosis in the cancer cells and augmenting endothelial cell survival to promote angiogenesis via activating the Akt pathway." (PMID 24009721, 2013). "The protein level of periostin in the cancer tissues was significantly higher than in the paratumor (P=0.000) and normal (P=0.017) tissues." (PMID 24273600, 2013). "The western blot analysis showed that the periostin level was elevated in the cancer tissue of the NSCLC patients." (PMID 24273600, 2013). "Periostin is found in normal skin, during tissue repair, and in pathological conditions, such as cancer." (PMID 24349533, 2013).
cancer (continued). "The periostin protein gray scale levels of cancer, paratumor and normal tissues were 1.810±0.415, 0.857±0.130 and 0.808±0.100, respectively." (PMID 24273600, 2013). "When PanIN samples were compared to PDACs, the most commonly up-regulated genes in the cancers were POSTN, COL1A2, SULF1, FN1, IGHM, VCAN and XIST, and these down-regulated were PGC and PPY." (PMID 23372777, 2013). "The protein level of periostin was elevated in the cancer tissue of the NSCLC patients compared with the normal (P=0.017) and paratumor (P=0.000) tissues." (PMID 24273600, 2013). "The protein level of periostin was detected in paired normal/paratumor/cancer tissues by a western blot analysis and the mRNA level in paired normal/cancer tissues was detected by quantitative polymerase chain reaction (qPCR)." (PMID 24273600, 2013). "Further studies showed that periostin is the ligand of αvβ3 and αvβ5 integrins in breast, colon and oral cancer cells." (PMID 24273600, 2013). "Cumulative evidence shows that high expression of periostin is frequently observed in various cancers and correlates well with malignant behavior." (PMID 22952986, 2012). "Periostin-promoted lymphangiogenesis was mediated by increased secretion of VEGF-C from cancer cells and by migration and tube formation via activation of Src and Akt in lymphatic endothelial cells." (PMID 22952986, 2012). "On the other hand, clinico-pathological studies showed that periostin was well correlated with lymph node metastasis in various cancers." (PMID 22952986, 2012). "It is interesting to examine the correlation between periostin and lymhangiogenesis in these types of cancer." (PMID 22952986, 2012). "Periostin has been reported to correlate with the process and facilitate the migration of the cancer cells." (PMID 21714934, 2011). "It has recently been reported that Periostin was frequently overexpressed in various types of human cancers." (PMID 21998657, 2011). "Though Periostin can promote the proliferation and the survival of several human cancer cell lines in vitro by inducing Akt/PKB pathway." (PMID 21714934, 2011). "For the majority of cancers investigated, periostin expression was found to be increased over normal tissue, but there are distinct exceptions where this pattern is reversed." (PMID 20109226, 2010). "Increased expression of periostin and lumican was observed in carcinoma as well as in stromal cell in the large majority of cases." (PMID 24281036, 2010). "The nature of periostin-producing cells in tumors is still under debate as separate studies reported a production of periostin by stromal cells whereas other experiments suggested that POSTN mRNA is detected in cancer cells." (PMID 18086302, 2007). "In line with this, a significant increase in periostin expression was measured in fibroblast-like stellate cells from pancreatic ductal adenocarcinoma tumors, a cancer characterized by excessive desmoplasia." (PMID 18086302, 2007). "POSTN plays a key role in promoting angiogenesis and pre-metastasis of various cancers." (PMID 41018265, 2025). "Consequently, although Smad2/3 signaling is highly active in cancer cells, its target genes differ from those regulated by Smad2/3 in CAFs, such as periostin." (PMID 39941916, 2025). "The synergistic effect of POSTN and other extracellular matrix proteins may lead to activated neural signals recruiting CAFs to synergistically promote cancer progression and immune evasion." (PMID 41147013, 2025). "Most current treatment strategies are unable to distinguish these isomers, which may lead to the inhibition of beneficial POSTN functions (such as tissue repair), and fail to effectively block the cancer-promoting effect." (PMID 41018265, 2025). "The disruption of periostin’s interaction with cellular surface receptors on cancer cells may represent a viable therapeutic strategy and could potentially disrupt the cross-talk between cancer cells and CAFs." (PMID 39941916, 2025).
cancer (continued). "Similarly, another study reported that periostin enhances gemcitabine resistance and promotes cancer cell invasiveness via the ERK1/2 and FAK/AKT pathways." (PMID 40437741, 2025). "However, in cancer cells, despite a high Smad2/3 positivity rate of 90%, periostin expression was notably low at only 0.6%." (PMID 39941916, 2025). "POSTN also showed interaction with protein tyrosine kinase 7 in HNSCC to promote cancer stemness." (PMID 39780187, 2025). "POSTN is expressed in various tissues, including bone, skin, and the heart, but its expression is markedly elevated in pathological conditions, particularly in cancer." (PMID 41018265, 2025). "POSTN, identified in bulk proteogenomic analysis, may also play a critical role in these cell communications and microenvironment remodelling during cancer cell dissemination." (PMID 40038875, 2025). "Additionally, periostin maintains cancer stem cells via Wnt signaling, and blocking it prevents metastasis." (PMID 40518514, 2025). "In veterinary medicine, these proteins contribute to better diagnosis and treatment of cancer in patients and may indicate potential animal models for studying relevant cancers in humans with POSTN and PDPN being among such proteins." (PMID 41361308, 2025). "The STRING analysis of ASPN in Canis lupus familiaris (accessed 10.03.2025) in the present study revealed its co-expression with periostin (POSTN), a secreted extracellular matrix protein involved in cancer stem cell maintenance and the metastatic progression of cancers." (PMID 40566602, 2025). "Periostin mRNA levels were significantly increased in ECF-R cancer cells." (PMID 40518514, 2025). "Specifically, cancer-associated fibroblasts (CAFs), a predominant stromal component, mediate extracellular matrix (ECM) deposition and remodeling by secreting collagen, fibronectin, and periostin." (PMID 41226014, 2025). "However, there are no reports, to the best of our knowledge, of the tissue expression of PN1-2 mRNA in TSCC and the inhibitory effect of POSTN exon 21-specific neutralizing antibody (PN21-Ab) on the progression of cancer." (PMID 39195230, 2024). "In particular, pathological POSTN with exon 17 is present in both stroma and cancer, but it is unclear whether the stroma or cancer pathological POSTN should be suppressed." (PMID 39272982, 2024). "Periostin (POSTN) produced by cancer cells induced secretion of the chemokine CC motif chemokine ligand 2 (CCL2) by endothelial progenitor cells (EPCs), which in turn promoted a metastatic phenotype in HCC cells by increasing CD36 expression through the CCR2/STAT3 signaling pathway." (PMID 39624081, 2024). "Finally, to investigate the role of the POSTN with exon 17 inhibition in both stroma and cancer in vivo, we treated POSTN exon 17 antibody (40, 100, 250, and 600 μg/mice) or control IgG (600 μg/mice) with the MDA-MB 231 human TNBC xenograft model." (PMID 39272982, 2024). "However, the inhibition of all POSTN (PN1–4) has been reported to aggravate cancer in several animal models." (PMID 39272982, 2024). "POSTN has the potential to serve as a biomarker for predicting the invasiveness of cancer cells." (PMID 39329988, 2024). "In cancer, stromal expression of POSTN is a predictor of poorer survival in CRC." (PMID 38275881, 2024). "In many cancers, POSTN is mostly found in the cancer stroma." (PMID 39195230, 2024). "In addition, it has been proven that a high expression of POSTN in cancer cells promotes their acquisition of resistance to hypoxia." (PMID 39272978, 2024). "In addition, we produced POSTN exon 17 skipping oligo with the exon skipping method to inhibit it in cancer cells." (PMID 39272982, 2024). "The inhibition of POSTN exon 17 in both stroma and cancer by antibody is beneficial in murine TNBC." (PMID 39272982, 2024).